IL6 (interleukin 6)
Diseases named in the same sentence as IL6 in open-access papers (continued):
Sharing a sentence is not in itself a finding about the gene and the disease.
adenomyosis (26 papers, 2012 to 2025). The growth of endometrial tissue inside the muscular wall of the uterine corpus. "In a recent study, we demonstrated that uterine IL-6 concentrations are elevated in adenomyosis patients and that this is associated with decreased endometrial receptivity." (PMID 36568084, 2022). "Together, these immunological and physiological alterations underscore a coordinated disruption of uterine homeostasis in adenomyosis, prompting us to consider the underlying mechanisms by which IL6–driven inflammation and STAT3 modulation impair tissue growth and remodeling." (PMID 41298316, 2025). "Although we did not detect sustained Stat3 mRNA elevation—likely due to negative feedback by SOCS3 —the persistent Il6 mRNA overexpression suggests that post-transcriptional activation of STAT3 or alternative pathways (e.g. MAPK) may underlie lesion progression in adenomyosis." (PMID 41298316, 2025). "The mRNA expression of IL-6 and IL-8 was the highest in the ectopic endometrium for the adenomyosis group, followed by eutopic and normal endometria." (PMID 36834456, 2023). "In patients with adenomyosis, the expression of several inflammatory cytokines, such as IL-1β, IL-6, IL-8, IL-10, TNF, NF-κB, MCP-1, and RANTES, is abnormal, and a variety of signaling pathways such as TLR437 and MAPK/ERK are involved." (PMID 36230643, 2022). "Eutopic endometrium (lining the uterus) and ectopic endometrium of adenomyosis lesions in the myometrium aberrantly display activation of interleukin 6 (IL-6) and ERK/MAPK signalling, although studies are limited." (PMID 35773139, 2022). "The systemic and local immune changes have been observed in women affected by adenomyosis, accompanied by the elevated levels of IL-6, IL-1β, IFN-α, TNF-α, and IFN-γ, and the coexistence of changes in inflammatory and anti-inflammatory signals." (PMID 34931128, 2021). "Similar to MPA and danazol treatment of adenomyosis 32, 33, mifepristone treatment inhibited the secretion of IL-6 in endometrial epithelial and stromal cells of adenomyosis in our experiments." (PMID 32038106, 2020). "Higher levels of endometrial IL-6 during the WOI in controlled ovarian stimulation (COS) cycles were observed in women with adenomyosis." (PMID 32933042, 2020). "The relationship between the expression of IL-6 and IL-8 and TLRs in EU and the pathogenesis of adenomyosis require more future research." (PMID 28779087, 2017). "In the context of adenomyosis, early IL-10 induction may represent a host attempt to counterbalance IL-6–driven inflammation and prevent excessive fibrosis." (PMID 41298316, 2025). "Targeting macrophage-related biomarkers, such as specific cytokines (e.g., TNF-α, IL-6) or macrophage surface markers (e.g., CD68), could provide diagnostic tools or therapeutic targets for adenomyosis." (PMID 40989079, 2025). "For example, IL-6, IL-10, and IL-22 show altered expression in adenomyosis lesions." (PMID 39595579, 2024). "However, adenomyosis disrupts this equilibrium, where an increase in IL-6 levels leads to the activation of the JAK2/STAT3 pathway, fostering EMT and enhancing cellular invasion capabilities." (PMID 39595579, 2024). "The expression of proinflammatory cytokine in adenomyosis may depend on TLRs, as the IL-6 and IL-8 expression was positively correlated with the expression of TLRs." (PMID 36834456, 2023). "Furthermore, the numbers of natural killer cells and macrophages have been found to be elevated in the eutopic endometrium of patients with adenomyosis along with increased levels of inflammatory markers (IL-1b and IL-6)." (PMID 36744089, 2023). "IL-6 and IL-8 have been reported to promote the inflammatory pathological state of adenomyosis." (PMID 34931128, 2021). "In addition, upregulation of IL6 was observed in primary culture of endometrial stromal cells (ESCs) from women with adenomyosis after co-culture with macrophages." (PMID 32933042, 2020).
adenomyosis (continued). "High expression of TLRs in EU and EC were positively correlated with IL-6 and IL-8, which may be involved in the inflammatory pathogenesis of adenomyosis." (PMID 28779087, 2017). "It was found in this study that the mRNA expression of IL-6 and IL-8 in EU was significantly higher than that in CE, and was the highest in EC (P < 0.01), which is consistent with previous studies, indicating that adenomyosis is an inflammatory pathological state." (PMID 28779087, 2017). "In addition, we analyzed the correlation between IL-6 and IL-8 and TLRs in adenomyosis patients and found that TLRs were positively correlated with corresponding IL-6 and IL-8 in EU and EC, of which TLR1, 2, 4, 5 and 9 were significantly positively correlated with IL-6 and IL-8." (PMID 28779087, 2017). "Studies have predicted that the IL-6 and ERK/MAPK pathways are abnormally activated in the eutopic endometrium of patients with adenomyosis." (PMID 36744089, 2023). "The Qiu treatment inhibited the expression of IL-1β, IL-6, and TNF-α in the tamoxifen-induced adenomyosis mice in a dose-dependent manner." (PMID 34931128, 2021). "And this activation was related to the elevated levels of IL-1β, IL-6, and TNF-α in serum and uterine tissue of adenomyosis mice." (PMID 34931128, 2021). "The elevated levels of IL-1β, IL-6, and TNF-α in serum and uterus tissues of adenomyosis model mice were also decreased after Qiu treatment." (PMID 34931128, 2021). "In the present study, we found that mifepristone reduces the secretion of IL-6 and TNF-α from endometrial epithelial and stromal cells in adenomyosis." (PMID 32038106, 2020). "Inflammatory mediators, including IL-6, TNF-α, IL-1β and IL-10, are involved in inflammatory pathway and contribute to the intense painful symptoms in adenomyosis 8-10." (PMID 32038106, 2020). "‘IL‐6 signalling’ (−log(P value) = 5.87) and ‘ERK/MAPK signalling’ (−log(P value) = 5.21) were the major pathways altered in eutopic endometrium of adenomyosis." (PMID 31576674, 2019). "Bioinformatic analysis predicted that IL‐6 signalling and ERK/MAPK signalling were activated in adenomyosis endometrium." (PMID 31576674, 2019). "Study has demonstrated that berberine has a protective effect on adenomyosis, a complication of PID, by inhibiting the expression of IL-6, IL-8, TGF-β, VEGF and MMP-2." (PMID 30555525, 2018). "Elevated IL6 and altered IL10 dynamics have also been reported in human endometrial tissues from patients with adenomyosis, supporting the translational relevance of these cytokine patterns, which are known to influence endometrial receptivity and implantation success." (PMID 41298316, 2025). "Isolated total RNA from endometrial biopsy samples collected during the window of receptivity were used to verify whether selected candidate genes LIF, SOCS3, FOS, JUNB, IL6 and IL10 were differentially expressed between adenomyosis and control groups." (PMID 32933042, 2020). "We tested the mRNA and protein expression of TLRs, and the mRNA expression of IL-6 and IL-8 in EU and EC of adenomyosis patients, and control endometrium without adenomyosis(CE)." (PMID 28779087, 2017). "In this review, we concentrated on VEGF, EGF, MMP2, IL-6, and TGF-β because we suspect that they may play a major role in the biological processes leading to the establishment and maintenance of adenomyosis." (PMID 26898650, 2016). "Therapeutically, monoclonal antibodies targeting IL-6 (e.g. tocilizumab) or JAK inhibitors (e.g. ruxolitinib) have already been tested in other inflammatory diseases and may represent candidate agents for repurposing in adenomyosis models." (PMID 41298316, 2025). "Indeed, some research reported different cytokine profiles in the endometrium of women with and without adenomyosis, with significantly higher levels of IL-6, IFN-γ, and monocyte chemoattractant protein-1 (MCP-1) in adenomyosis patients." (PMID 38999290, 2024).
adenomyosis (continued). "Our findings showed that mifepristone significantly decreased the expressions of IL-6 and TNF-α in both endometrial epithelial and stromal cells of adenomyosis, which may be the reason that mifepristone is more effectively than progestins in the relief of adenomyosis-associated pain." (PMID 32038106, 2020). "Despite LIF, IL6, IL10, JUNB, FOS and SOCS3 showing no statistically altered expression patterns between study groups, their lower expression levels were observed in the adenomyosis group." (PMID 32933042, 2020).
chlamydial infection (26 papers, 2008 to 2025). "Induction of inflammatory cytokines such as IFN-γ and interleukin-6 (IL-6) in response to chlamydial infection likely causes sequestration of free iron by the activity of the mononuclear phagocytic system, which includes both cellular and systemic regulatory pathways (20, –, 27)." (PMID 29468197, 2018). "In the case of C. trachomatis infections resulting in tubal infertility, long-term tubal adhesion IL-6 is overexpressed, but it is also detected, for example, in the serum of asymptomatic patients with chlamydial infection." (PMID 40647668, 2025). "IL-6 is required to control chlamydial infection by limiting pathogen replication and colonization at both high and low doses of Chlamydia muridarum." (PMID 38396724, 2024). "The role of IL-6 in chlamydial infection and the pathological effects thus induced has been controversial." (PMID 34093528, 2021). "IL-6 is required for controlling chlamydial infection by limiting replication and colonization by the pathogen, at either high dose or low dose of Chlamydia muridarum (C. muridarum)." (PMID 34093528, 2021). "IL-6 and IL-8 are inflammatory cytokines and both of them are highly induced in the Fallopian tube upon chlamydial infection as well as ectopic implantation." (PMID 26840308, 2016). "Studies investigating the cytokine and chemokine response to chlamydial infection have shown up-regulation of IL-1α, IL-6, IL-11, TGF-β1, GM-CSF, GRO-α and IL-8 in C. trachomatis-infected HeLa cells." (PMID 25019934, 2014). "Preliminary data presented here indicates that the IL-6 induction in response to the externally supplemented chlamydial stress response proteases and live chlamydial infections involved MEK pathways." (PMID 24238294, 2013). "In an attempt to mimic chronic chlamydial infections, Macaca nemestrina fallopian tubes received repeated C. trachomatis infections, which resulted in fibrosis and elevated IL-6, IL-10, IL-2, and IFNγ levels." (PMID 22894815, 2012). "The reduction in bacterial numbers and IL-6 concentrations, and the clinical safety of 405 nm irradiation, supports further studies evaluating its use as a phototherapy against chlamydial infections within the conjunctival and reproductive tract mucosae." (PMID 22894815, 2012). "In the C3−/− mice the lung tissue concentrations of IFN-γ and TNF-α, two key cytokines in the defense against chlamydia, and of IL-6 and IL-10, were either similar to or even higher than for WT controls." (PMID 23189195, 2012). "In this study, we demonstrated elevated IL-6 levels post-chlamydial infection compared to uninfected cells (P < 0.005)." (PMID 22894815, 2012). "Although pleiotropic in nature, IL-6 is strongly correlated with pathogenesis in chlamydial infection." (PMID 19698128, 2009). "Further upon chlamydial infection, mononuclear cells are triggered to release a number of proinflammatory cytokines including TNF-α, IL-1, IL-6 and IL-8 and many studies have reported association between cytokine profiles and immunopathogenic mechanisms." (PMID 18828896, 2008). "Chlamydial infection induces the release of pro-inflammatory cytokines, such as interleukin (IL)-6 and tumour necrosis factor-alpha (TNF-α), and activates the innate immune response, which subsequently amplifies inflammation, particularly in patients with IVIG-unresponsive KD." (PMID 41383607, 2025). "IL-6 is important in the immune defense against chlamydial infection." (PMID 38396724, 2024). "This may be further magnified by other immune cells such as monocytes, which have been shown to elevate the production of IL-6 and IL-8 in a co-culture model of chlamydial infection of Hela and THP-1 cells." (PMID 36870960, 2023). "Furthermore, while IL-6 promotes host defense against chlamydial infection by balancing inflammatory and immune responses, this IL also exacerbates chlamydial pathogenicity through its involvement in inflammatory pathology." (PMID 34093528, 2021).
chlamydial infection (continued). "In addition, significantly reduced IL-6 and IL-8 mRNA expression levels were observed for reactivated Chlamydiae under hypoxia compared to a persistent chlamydial infection under normoxia." (PMID 24783060, 2014). "Fifteen patients had elevated IL-6 levels (>1.5 pg/mL), including 8 with a current symptomatic STI (3 chlamydia and 6 gonorrhea, including 1 with both)." (PMID 33796598, 2021). "Compared to group (i), we observed increased secretion of five cytokines (MIF/GIF, Serpin E1, RANTES, IL-6, IL-8) and five chemokines (ENA-78, IL-16, IP-10, MIG, MIP-1α/β) following wIRA/VIS-exposure, chlamydial infection or both." (PMID 25019934, 2014). "We also detected an increase of MIF/GIF after chlamydial infection, a pro-inflammatory cytokine promoting the production of tumor necrosis factor (TNF), IFN-γ, IL-1β, IL-2, IL-6 and IL-8." (PMID 25019934, 2014). "Chlamydial infection, irradiation, and the combination of both showed a similar release pattern of a subset of pro-inflammatory cytokines (MIF/GIF, Serpin E1, RANTES, IL-6, IL-8) and chemokines (IL-16, IP-10, ENA-78, MIG, MIP-1α/β) from host cells." (PMID 25019934, 2014). "We found that chlamydial infection alters the morphology of monocytes and trigger the release of pro-inflammatory cytokines TNF-α, IL-8, IL-1β and IL-6." (PMID 21249123, 2011). "The relative increase in production of important cytokines (TNF-α, IL-6, IL-2 and INF-γ) in the AHCC-fed group may lead to decreased chlamydia genital infection in the stress model." (PMID 27790645, 2015). "Chlamydial infection of mice lead to the development of CD4+ T cells that significantly secreted IL-6, IL-10, and GM-CSF, but not IL-4, in response to C. muridarum re-stimulation." (PMID 18700040, 2008). "In this study, we did not report significantly increased levels of IL-6, IL-8, or RANTES upon chlamydial infection (alone or in combination with wIRA/VIS irradiation)." (PMID 30524392, 2018). "qPCR was used to examine mRNA expression for Th1 (IFNγ), Th2-promoting (IL6, IL10) and Th17 (IL17A) cytokines, along with CD4 and CD8 in whole blood of koalas (n = 74) from Mt Eccles and Raymond Island in Victoria, Australia, with and without natural chlamydial infection." (PMID 31371797, 2019).
chronic hepatitis B (26 papers, 2005 to 2025). "Increased serum levels of IL-6 have been associated with high risk to develop HCC in patients with chronic hepatitis B and C; accordingly, high serum IL-6 has been frequently observed in patients with HCC and it was associated with a poor prognosis." (PMID 23533994, 2013). "The novel HBV preS1 mutation W4P may contribute to HCC development in men with chronic hepatitis B in an IL-6-dependent manner." (PMID 25645622, 2015). "IL-17A can also significantly stimulate monocytes and DCs to express their ligand (IL-17R) and produce pro-inflammatory cytokines such as IL-1β, TNF-α, IL-6, etc., which are important for liver damage during progression of chronic hepatitis B." (PMID 33435966, 2021). "The breakdown of platelets in the spleen and increased levels of IL-6 production secondary to inflammation in the fibrosis process were thought to contribute increased MPV in patients with chronic hepatitis B (CHB)." (PMID 27716426, 2016). "The high induction of IL-6, by our extracts, suggests that these extracts may aid in the clearance of the virus during chronic hepatitis B infection." (PMID 41216486, 2025). "Furthermore, chronic hepatitis B patients exhibited an immune response to MAG1 characterized by elevated levels of Interleukin-6 (IL-6) and interleukin-1β (IL-1β) cytokines." (PMID 41041334, 2025). "Indeed, increased serum IL-38 has been found in chronic hepatitis B sufferers, indicating ongoing liver damage, as reflected by its positive correlation with IL-6 and/or AST." (PMID 35948957, 2022). "To examine the change in immune balance during the treatment of patients with chronic hepatitis B with entecavir and thymosin a1, we further analyzed the expression of immune factors such as IL-6, IL-12, IFN-γ, and TNF-α at the 12th, 24th, and 48th week of treatment cycles." (PMID 36596032, 2022). "This study suggests that the W4P mutation during the natural course of chronic hepatitis B infection may contribute to HCC development, particularly in male patients, in an IL-6-dependent manner." (PMID 25645622, 2015). "Previous studies have shown that HMGB1 regulated Treg/IL17 ratio in patients with chronic hepatitis B, in which HMGB1 was significantly higher and induced Th17 cells but suppressed Tregs via TLR4 and IL6 pathway." (PMID 33679792, 2021). "In conclusion, our study suggest that BMD of femur, serum IL-2r, IL-6, IL-8, PTH, and CTX levels were higher in children with chronic hepatitis B treated with IFN-alpha alone or combination with lamivudine than in healthy children." (PMID 16171525, 2005). "Despite coexisting chronic hepatitis B and thalassemia, the patient’s immune function was not significantly impaired, with inflammatory markers such as PCT, CRP, and IL-6 remaining within normal ranges." (PMID 39728308, 2024). "While serum IL-2r (p = 0.002), IL-6 (p = 0.001), IL-8 (p = 0.013), PTH (p = 0.029), and CTX (p = 0.021) levels were higher in children with chronic hepatitis B than in healthy controls, there was no significant different in respect to serum IL-1β, TNF-α and osteocalcin levels." (PMID 16171525, 2005).